FIRRM (FIGNL1 interacting regulator of recombination and mitosis)
Description:
Forms a complex with FIGL1, which regulates DNA double-strand break (DSB) repair via homologous recombination (HR). The FIGNL1-FIRRM complex is essential for resolution of homologous recombination intermediates in response to DNA interstrand cross-links (ICLs). The complex regulates HR by promoting disassembly of RAD51 filaments from DNA and chromatin, thereby preventing DNA damage-independent RAD51 loading and persistent DNA accumulation of RAD51 recombinases. It also regulates HR during meiosis by promoting dissociation of DMC1 filaments from DNA (By similarity). Within the complex, provides the ATPase activity to disassemble DMC1 and RAD51 filaments, while FIRRM directly binds single-stranded DNA to facilitate this unloading. Independently of FIRRM, slso acts as a regulator of PLK1 kinase activity at kinetochores that promotes faithful chromosome segregation in prometaphase by bridging kinase and phosphatase activities. Phosphorylation of FIRRM by PLK1 negatively regulates its interaction with the phosphatase, PPP1CC, thus creating a negative feedback loop for maintaining proper PLK1 kinase activity during mitosis.
Synonyms: FLIP; APOLO1; C1orf112; FLJ10706; MEICA1
Tractability: PROTAC: ubiquitination databases record sites on it.
Gene: Protein-coding gene on chromosome 1 (169,662,007 to 169,855,456, forward strand). Ensembl gene ENSG00000000460.
Subcellular location: Chromosome; Nucleus; Chromosome, centromere, kinetochore; Chromosome, centromere; Midbody; Cytoplasm, cytoskeleton, spindle
Subcellular location (Human Protein Atlas): Nucleoplasm; Nucleoli
Pathways (Reactome):
Cell Cycle: Resolution of Sister Chromatid Cohesion
DNA Repair: Resolution of D-loop Structures through Holliday Junction Intermediates
Reproduction: Meiotic recombination
Gene Ontology:
Molecular function: protein binding; protein kinase binding; single-stranded DNA binding
Biological process: chromosome segregation; DNA recombinase disassembly; interstrand cross-link repair; mitotic cell cycle; negative regulation of double-strand break repair via homologous recombination; regulation of protein kinase activity; double-strand break repair involved in meiotic recombination; homologous recombination
Cellular component: chromosome, centromeric region; DNA repair complex; kinetochore; midbody; nucleolus; nucleoplasm; nucleus; site of DNA damage; spindle midzone; cytosol; chromosome; spindle
Genetic constraint (gnomAD): Loss-of-function variants: 42 observed, 61.41 expected, observed/expected ratio (o/e) 0.68, 90% interval 0.53 to 0.88. The upper end of that interval is the gene's LOEUF score, 0.88, which puts it in group 3 of 6, group 1 being the genes least tolerant of losing a copy. Missense variants: 616 observed, 719.28 expected, observed/expected ratio (o/e) 0.86, 90% interval 0.8 to 0.92. Synonymous variants: 238 observed, 258.53 expected, observed/expected ratio (o/e) 0.92, 90% interval 0.83 to 1.02.
Homologues: Orthologues: chimpanzee FIRRM (99% identical), macaque FIRRM (96% identical), guinea pig FIRRM (81% identical), pig FIRRM (81% identical), rabbit FIRRM (80% identical), rat Firrm (73% identical), mouse Firrm (72% identical), tropical clawed frog firrm (55% identical), zebrafish firrm (45% identical).
Diseases named in the same sentence as FIRRM in open-access papers:
FIRRM is named in the same sentence as 46 diseases in open-access papers, as found by Europe PMC text mining. Sharing a sentence is not in itself a finding about the gene and the disease.
FIRRM shares sentences with these, for which no sentence is quoted: cancer (8 papers); tumor (7); breast carcinoma (4); cervical cancer (3); gastric cancer (3); lung carcinoma (3); sarcoma (3); bladder cancer (2); central nervous system cancer (2); colorectal cancer (2); endometrial cancer (2); Fanconi anaemia (2); glioma (2); head and neck squamous cell carcinoma (2); acne (1); adrenocortical carcinoma (1); amyotrophic lateral sclerosis (1); Astrocytoma (1); Astroglioma (1); bladder urothelial carcinoma (1); bone tumors (1); brain glioma (1); cervical squamous cell carcinoma (1); cholangiocarcinoma (1); colon adenocarcinoma (1); desmoid tumor (1); diffuse astrocytoma (1); endocervical adenocarcinoma (1); esophageal cancer (1); glioblastoma multiforme (1).
A further 16 diseases each share a sentence with FIRRM in 1 paper.